HIF1A (hypoxia inducible factor 1 subunit alpha)
Diseases named in the same sentence as HIF1A in open-access papers (continued):
Sharing a sentence is not in itself a finding about the gene and the disease.
cancer (continued). "In addition, elevated PTBP1 levels have been shown to support aerobic glycolysis and enhance translation of hypoxia-inducible factor 1α (HIF-1α), which enables cancer cells to survive hypoxic conditions associated with altered ROS homeostasis." (PMID 22911749, 2012). "The accumulation of HIF-1α has been associated with cancer causing mutations including loss of VHL or PTEN and activation of signalling via RTK, non-RTK and G-protein-coupled receptor through activation of the PI3K and ERK MAPK pathways in a cell type-specific manner." (PMID 21897387, 2011). "This discrepancy may come from the different cell types (cancer cell vs non-cancer cells), as the mechanism underlying the activation of HIF-1α is specifically tailored according to cell type." (PMID 21119667, 2011). "Hypoxia-inducible factor 1α (HIF-1α), a transcription factor which is overexpressed in the majority of human carcinomas and controls central metastasis-associated pathways, was shown to increase anchorage-independent growth by downregulation of the α5 integrin." (PMID 20492690, 2010). "Meta-analysis of the HIF-1α 1790 G/A polymorphism and cancer association." (PMID 20035632, 2009). "Thus, the association between the HIF-1α 1772 C/T and 1790 G/A polymorphisms and cancer requires further investigation." (PMID 20035632, 2009). "The HIF-1α gene was previously found to be implicated in the development and progression of cancer." (PMID 20035632, 2009). "However, studies focusing on the association of the HIF-1α gene polymorphism with cancer susceptibility had controversial conclusions." (PMID 20035632, 2009). "Second, our meta-analysis suggests that carcinogenic mechanism may differ in different cancers and HIF-1α 1790 G/A polymorphism may exert varying effect." (PMID 20035632, 2009). "For the HIF-1α 1772 C/T polymorphism, our meta-analysis on the available studies showed that the T allele and genotype TT were significantly associated with increased cancer risk." (PMID 20035632, 2009). "Meta-analysis of the HIF-1α 1772 C/T polymorphism and cancer association." (PMID 20035632, 2009). "The molecular mechanism underlying HIF-1α expression in cancer warrants particular attention." (PMID 17166265, 2006). "HIF-1α overexpression has been linked to a poor clinical outcome in some types of human cancers." (PMID 17166265, 2006). "Poorly differentiated carcinomas were associated with nuclear HIF-1α and membranous CA9 expression." (PMID 15558070, 2005). "Thus, blocking proteins linked to EMT, mitochondrial functions, and HIF-1α could be one way to treat cancer since it would prevent the body's reaction to hypoxia." (PMID 39547513, 2024). "Hence, IL-6 could be a cancer progression inducer upregulated by hypoxia since the activation of this signaling pathway in hypoxic conditions by HIF-1α is associated with several steps of the metastatic cascade in which the MMPs are involved." (PMID 38069210, 2023). "Furthermore, HIF-1α expression has been linked to poor prognosis in different cancers." (PMID 36939902, 2023). "This is the case with HIF1A, the most pivotal gene regulating metabolic pathways related to hypoxia, which is further implicated in proliferation, energy metabolism, invasion, and metastasis in a series of human cancers, and has been viewed as a highly promising therapeutic target." (PMID 36551790, 2022). "Therefore, targeting HIF-1α-associated signaling could serve as a potential therapeutic target to improve the effectiveness of clinical cancer therapies." (PMID 35236823, 2022).
cancer (continued). "Finally, our laboratory has recently shown that infection of gastric cells with H. pylori increases the expression of hypoxia induced factor-1α (HIF-1α), a transcription factor considered crucial for inducing metabolic changes associated with the development of cancer." (PMID 36313672, 2022). "Interestingly, our data suggest that HIF1α has a mutation rate of 5% in pan-cancer." (PMID 35860430, 2022). "Therefore, in this study, we considered statistical meta-analysis to make a consensus decision about the association of HIF1A gene (1772 C/T and 1790 G/A) polymorphisms with several disease risks excluding cancers, giving the weight on large sample size and appropriate statistical modeling." (PMID 35972942, 2022). "Therefore, HIF-1α-associated signaling has been recognized as an important cancer drug target." (PMID 35236823, 2022). "HIF-1α may increase the risk of cancer in patients with COPD." (PMID 36338690, 2022). "The higher levels of ROS found in cancer cells have been linked to the activation of numerous transcription factors, of which nuclear factor kappa-light-chain-enhancer of activated B cells (NF-κB) and hypoxia-inducible factor 1-alpha (HIF-1α) are some of the most important." (PMID 34829672, 2021). "We propose that inhibition of NER represents a previously unrecognized feature of the diabetic impairment of HIF-1α that may contribute significantly to genomic instability, enhanced susceptibility to endogenous and exogenous DNA damaging agents, and increased cancer risk." (PMID 34426491, 2021). "Besides, MUC1 induces the expression of PDGF-A in cancer cells in association with HIF-1α." (PMID 33836774, 2021). "Thus, FTIs may be an effective agent for TNBCs with elevated expression of HIF‐1α, which is associated with cancer aggressiveness." (PMID 33773069, 2021). "Furthermore, rs11549465, rs11549467 and rs2057482 in HIF-1α may modify cancer susceptibility in an ethnicity- and type-specific manner." (PMID 33154192, 2020). "Finally, to dissect the mechanism how TR4/lincRNA-p21 axis can alter the chemo-sensitivity in PCa, we focused on the HIF-1α, as an early study indicated that lincRNA-p21 might be linked with HIF-1α in regulating Warburg effect in cancer." (PMID 31748715, 2020). "Moreover, SNPs in HIF-1α that modify cancer susceptibility have been studied extensively." (PMID 33154192, 2020). "However, the stabilization of mammalian HIF-1α has been implicated in tumor growth and cancer development and may therefore be harmful." (PMID 31941032, 2020). "Thus, it is biologically plausible that an amino acid substitution in rs11549465 (Pro>Ser) may lead to the dysfunction of HIF-1α, hence increasing cancer susceptibility." (PMID 33154192, 2020). "Furthermore, both Hif-1α and Hif-2α are frequently overexpressed in NSCLC correlating, in some cases, with poor prognosis and Hif-1α expression is associated with resistance to cancer therapy, including EGFR (epidermal growth factor receptor 1) inhibitors in NSCLC." (PMID 31795465, 2019). "In addition, curcumin was found to abrogate cancer associated fibroblast-induced prostate cancer cells invasion by downregulating monoamine oxidase A (MAOA)/mammalian target of rapamycin (mTOR)/hypoxia-inducible factor-1α (HIF-1α) signaling pathway." (PMID 31547193, 2019). "Furthermore, hypoxia-reoxygenation injury in cancers may stabilize HIF-1α, indicating that its constitutive upregulation may be caused by the cyclic oxic-hypoxic cycles which happen in premalignant cancers." (PMID 28077918, 2016). "In a recent metaanalysis of 1258 RCC patients on the prognostic significance of HIF1α or HIF2α found high nuclear HIF1α expression was associated with poor overall survival, while high cytoplasmic expression of HIF2α was associated with poor cancer specific survival." (PMID 27244898, 2016).
cancer (continued). "Recent studies demonstrated that another SNP located in ODD of HIF-1α, 1772 C > T (rs11549465), may lead to an amino acid change from proline 582 to serine (P582S) and are reportedly associated with renal, head and neck, prostate, lung, and pancreatic cancers." (PMID 25302049, 2014). "Besides, the expression of HIF1α is associated with the prognosis of cancer patients." (PMID 24567056, 2014). "Secondly, we asked whether the reduced susceptibility of the cancer cells towards ascorbate under hypoxic conditions was merely driven by the reduced O2 partial pressure (essential for radical formation) or whether HIF1α-signalling might also be involved in the observed cellular resistance." (PMID 24330097, 2014). "Finally, since it was shown that a-KG mimics may inhibit human Hypoxia-Inducible-Factor (HIF) hydroxylases PHD1 and PHD2 causing HIF accumulation and consequent cancer cell protection, we tested 3195 for induction of HIF1α accumulation in HeLa cells." (PMID 24489688, 2014). "Thus, the relationship between HIF-1α polymorphisms and cancers requires further investigation." (PMID 24260383, 2013). "In addition to up-regulation of VEGF expression, HIF-1α itself has been found to be an important mediator of survival and angiogenesis and its over expression in the majority of the human cancers has been associated with patient mortality and poor response to treatment." (PMID 20398289, 2010). "Our earlier findings indicate that increased FA supply activates the FA/HIF‐1α/CCL2 axis in cancer cells." (PMID 41160815, 2026). "In HCC, SENP1 was demonstrated to promote hypoxia-induced cancer stemness by deSUMOylating HIF-1α, thereby establishing a positive feedback loop." (PMID 41438340, 2026). "Accordingly, treatment with CM derived from cocultured cancer cells led to increased HIF‐1α levels compared to monoculture‐derived CM." (PMID 41160815, 2026). "It is worth mentioning that LINK‐A plays a role in controlling important pathways related to cancer, such as HIF1α and AKT signaling." (PMID 41459628, 2026). "Vitamin D inhibited lactate metabolism and HIF-1α expression in fibroblasts while suppressing TCA cycle activity in cancer cells, suggesting a potential role in disrupting oncogenic metabolic crosstalk." (PMID 41595213, 2026). "Activation of HIF‐1α induced by FA influx increases CCL2 expression in cancer cells, which subsequently leads to lipolysis in nearby adipose tissue by activating peroxisome proliferator‐activated receptor alpha (PPARα) signaling." (PMID 41160815, 2026). "Menopause status, BMI, and HIF1A expression were significant stimulating factors that influenced the cancer presence in patients compared to control groups." (PMID 39888575, 2026). "α-Humulene epoxide II exhibited antineoplastic activity, functioned as an apoptosis agonist, and inhibited cancer-related targets such as HIF1A and MMP9." (PMID 41346770, 2026). "Hypoxia, in particular through the HIF1A transcription factor, was implicated in the expression of ANGPTL4 in cancer cells, in presumably non‐senescence contexts." (PMID 41347893, 2026). "Glycolytic products activate specific signaling pathways, such as hypoxia-inducible factor-1α (HIF-1α), which further facilitates cancer cell metastatic potential." (PMID 41535762, 2026). "HIF‐1α with its downstream metabolites can be targeted effectively through TNPs as a new approach for cancer therapy." (PMID 41521160, 2026). "Treatment methods exist to enhance both the stability and activity levels of HIF‐1α during cancer interventions." (PMID 41521160, 2026). "ANGPTL4 was previously reported to be upregulated in cancer cell lines by the HIF1A (Hypoxia Inducible Factor 1 Subunit Alpha) transcription factor during hypoxia." (PMID 41347893, 2026).
cancer (continued). "These nanosystems demonstrate excellent potential to advance cancer therapy since their delivery of HIF‐1α inhibitors in combination with glycolytic enzyme control and chemotherapy treatment and radiotherapy administration enables better outcomes." (PMID 41521160, 2026). "USP29 interacts with HIF-1α, reduces its poly-ubiquitination and protects it from proteasomal degradation across multiple cancer cell lines." (PMID 42125859, 2026). "Our comprehensive analysis of cytokine arrays and cocultured cancer cells revealed a significant increase in CCL2 driven by ADSC‐derived FAs among the target cytokines of HIF‐1α." (PMID 41160815, 2026). "Versican (VCAN)-AS1 is an endogenous RNA that targets signal transducer and activator of STAT3 to inhibit miR-106a-5p and promotes the growth of cancer cells by blocking the STAT3/HIF-1α axis." (PMID 41614928, 2026). "Inhibitors of JAK1/2 or HIF1α or drugs targeting their downstream signaling pathways have great potential for cancer therapy." (PMID 41520505, 2026). "MiR-143-5p prevents the growth and spread of cancer cells as well as the formation of tumors by post-transcriptionally inhibiting the production of HIF-1α and GLUT1." (PMID 41614928, 2026). "Acriflavine, a FDA‐approved inhibitor of HIF‐1α, demonstrated promising therapeutic effects in controlling the progression of various diseases, including cancer." (PMID 41482854, 2026). "This environment led to an elevated level of HIF-1α in cancer cells, which correlated with increased expressions of Snail and Slug, resulting in cancer metastasis." (PMID 39926198, 2025). "HIF-1α is a master regulator that enables cancer cells to adapt to hypoxic conditions by orchestrating transcriptional programs." (PMID 41281744, 2025). "This flexibility stems from the dynamic regulation of the glycolysis/OXPHOS balance in cancer cells through molecular switches such as HIF-1α." (PMID 40754534, 2025). "STAT3 plays a crucial role in advanced cancers by promoting glycolysis through the transcriptional activation of HIF-1α and HK2 in vitro." (PMID 39859445, 2025). "Increased hypoxia-inducible factor 1-alpha (HIF-1α) expression in numerous cancers correlates with poor survival." (PMID 40272602, 2025). "HIF-1α enhances mitochondrial metabolism and supports cancer cell survival, while also promoting MMP-9 expression." (PMID 41303321, 2025). "Here, upregulated proteins falling below the line of identity followed the HIF-1α pattern and included products of cancer-wide conserved HIF-1α target genes." (PMID 40552983, 2025). "HIF-1α profoundly influences the immune response and therapeutic outcomes in cancer by shaping the TME." (PMID 39981236, 2025). "Excess estrogen activates the PI3K/Akt pathway and HIF-1α, promoting the progression of cancer by inducing VEGF, a key angiogenic factor." (PMID 39996906, 2025). "CRLX101 is a HIF-1α directed nanoparticle-drug conjugate transporting camptothecin (topo I-inhibitor) to cancer cells." (PMID 39762846, 2025). "The mutual counter-regulation between TSGA10 and HIF-1α, which integrates thermoregulation with metabolic reprogramming, has profound implications for cancer." (PMID 40507237, 2025). "Aberrant activation of mTOR is frequently observed in tumorigenesis, leading to the buildup of HIF-1α and subsequent stimulation of cancer cell growth." (PMID 39965249, 2025). "Given that hypoxia-inducible factor-1α (HIF-1α) plays a significant role in cancer development and progression, it has been an intriguing therapeutic target for cancer research." (PMID 41514626, 2025). "Overexpression of SLC10A1, which inhibits the production of Ado and decreases HIF‐1α mRNA and protein expression in cancer cells, is consistent with the reduced expression of HIF‐1α in AR 292 and AR 357‐treated PCa cell lines." (PMID 40181576, 2025).
cancer (continued). "IER3 (immediate early response 3) and HIF1A (hypoxia-inducible factor 1-alpha) transcriptionally regulates glycolytic genes glycolytic genes promoting a Warburg-like glycolytic shift in cancer cells." (PMID 40475528, 2025). "Overall, compared to those of LSEC and LSCC, DR‐LSCC showed upregulated expression of microtubule stabilization genes like ALK gene, metabolic gene GSK3B, and a slight increase of hypoxia gene HIF1A in the KEGG hsa05200 cancer pathway." (PMID 40385549, 2025). "Similar to EFNA3, the transactivation of NDRG1-OT1 by HIF-1α can enhance cancer cell growth and migration by sponging miR-875-3p." (PMID 40004471, 2025). "Clinical studies evaluate a range of medications targeting HIF‐1α, a protein involved in cancer growth." (PMID 40567251, 2025). "Numerous studies have shown that VHL is an E3 ligase that mediates HIF-1α protein ubiquitination, and the reduction of its degradation, in turn, is caused by the VHL deficiency promoting cancer progression." (PMID 39920992, 2025). "The roles of HIF-1α and HIF-2α in promoting tumorigenesis are well established and often considered hallmarks of cancers associated with poor prognosis." (PMID 39470609, 2025). "We show here for the first time that 2-aminopyrrole derivative 2-ANPC exhibits high potency in interacting with HIF-1α and downregulates its expression in multiple cancer cell lines in vitro." (PMID 41514626, 2025). "These multifaceted roles position HIF-1α as a key player in cancer progression and resistance to therapy, particularly in hypoxia-driven conditions." (PMID 39981236, 2025). "Park and colleagues reported that licochalcone A is the most prevailing bioactive metabolite in G. uralensis, which reduced the cancer cells’ growth and the activation of HIF-1α mediated by hypoxia." (PMID 40599794, 2025). "This was associated with the upregulation of ACE2 and the downregulation of pro-cancer biomarkers, including HIF-1α, MMP-9, and β-catenin." (PMID 41303321, 2025). "It is commonly known that a promising treatment approach for cancer involves strategically targeting HIF-1α and HIF-2α." (PMID 40004471, 2025). "Guzy and Schumacker specifically addressed this paradox of increased ROS generation during hypoxia, while Semenza’s review highlighted the significance of these HIF-1α-mediated mechanisms in cancer progression and potential therapeutic interventions." (PMID 40507237, 2025). "Understanding the mechanisms governing HIF‐1α stability is crucial for developing novel therapeutic strategies targeting HIF‐1α signaling pathways in cancer and other diseases." (PMID 40227962, 2025). "Heddleston found that increased HIF1α leads to an increased level of cancer stem cells (CSCs), which allows for the rapid growth of tumors and increased levels of VEGF." (PMID 40806669, 2025). "Research has found that HIF-1α is overexpressed in various cancers, such as brain, breast, and oropharyngeal cancers, promoting the proliferation and metastasis of cancer cells." (PMID 40421268, 2025). "Evidence is mounting that lncRNAs regulated by hypoxia are involved in cancer cell progression and HIF-1α-mediated transcriptional activation." (PMID 40597665, 2025). "Epigenetic modifications of NF-kB, STAT3, or HIF-1α in cancer cells can enhance the production of cytokines and growth factors that favor macrophage recruitment, survival, and activation, further inhibiting immune responses." (PMID 40564180, 2025). "Our findings highlight that a high WWOX/HIF1A ratio correlates with favourable prognosis across multiple cancers by promoting oxidative metabolism, enhancing DNA repair, maintaining ECM integrity, and supporting immune surveillance." (PMID 41007296, 2025). "HIF‐1α, activated in hypoxic tumors, regulates survivin expression through hypoxia‐responsive elements in its promoter region, enhancing cancer cell transcription after irradiation." (PMID 39535730, 2025).